CDO1 (cysteine dioxygenase type 1)
Diseases named in the same sentence as CDO1 in open-access papers (continued):
Sharing a sentence is not in itself a finding about the gene and the disease.
schizophrenia (1 paper, 2015). A major psychotic disorder characterized by abnormalities in the perception or expression of reality.
steatosis (1 paper, 2023). Increased lipid within the cytoplasm of cells. "Our in vitro experiments verified that Cdo1 can alleviate hepatocyte steatosis by promoting mitochondrial biogenesis and FAO." (PMID 38110408, 2023). "In the mechanistic study, we demonstrated that Cdo1 tethered Camkk2 to AMPKα, which promotes the AMPK activation to improve hepatocyte steatosis." (PMID 38110408, 2023).
triple-negative breast carcinoma (1 paper, 2022). An invasive breast carcinoma which is negative for expression of estrogen receptor (ER), progesterone receptor (PR), and human epidermal growth factor receptor 2 (HER2). "Recently, CDO1 was found to be closely linked to erastin-induced ferroptosis in triple negative breast cancer cells, whereas silencing CDO1 expression blocked ferroptosis in GC cells." (PMID 36526626, 2022).
vulva cancer (1 paper, 2012). A primary or metastatic malignant neoplasm involving the vulva. "CDO1 expression was clearly detected in most corresponding normal tissues (N) in the array, and down-regulated in tumors in more than 50% of patients with colon, stomach, pancreas, thyroid, skin, kidney, bladder, lung, breast, ovary, uterus, cervix and vulva cancer." (PMID 23028699, 2012).
tumor (51 papers, 2010 to 2026). "Previous research has indicated that CDO1 is frequently silenced in tumors due to the high methylation of its promoter, and is associated with tumor chemo-sensitivity and prognosis." (PMID 38308276, 2024). "The fact that no cancer was found to be caused by altered Cdo1 function alone indicates that the tumor suppressor role of Cdo1 is mild." (PMID 38672271, 2024). "Correlation analysis uncovered that tumor sizes in patients with low CDO1 protein level were significantly larger than those with high CDO1 expression, suggesting that CDO1 deficiency probably supported hyperproliferation in GC cells (p = 0.0027)." (PMID 36526626, 2022). "We found that CDO1 promoter hypermethylation was cancer prone and strongly associated with tumor malignancy." (PMID 29161283, 2017). "In this study, CDO1 hypermethylation was significantly associated with GBC tumor progression parameters, if the CDO1 methylation cut-off value of 17.7, which was meaningful from a prognostic point of view, was used." (PMID 29161283, 2017). "Furthermore, the loss of CDO1 is thought to be responsible for tumor progression in vitro by acting on multiple signaling pathways." (PMID 42265380, 2026). "Therefore, from the perspective of Cdo1, this mutation is favorable for the tumor-suppressing effect of Cdo1." (PMID 38672271, 2024). "Hypermethylation of cysteine dioxygenase 1 (CDO1) promoter is specific to IPMN and may increase with IPMN tumor progression, suggesting that CDO1 is a potential diagnostic marker of pancreatic cystic diseases." (PMID 36874143, 2023). "Any of these mechanisms could contribute to its growth suppressive function in vivo, but additional work is needed to evaluate the consequence of CDO1 loss in the relevant tumor microenvironment." (PMID 31107239, 2019). "In addition, when the association of tumor diameter with the CDO1 TaqMeth V was considered, the cutoff value reflecting the most dismal prognosis was 2.8 cm." (PMID 30677088, 2019). "Although we could not conclude that accumulation of promoter DNA methylation of CDO1 is a cause or a result of tumor progression, many reports have described the functional involvement of CDO1 in cancer progression." (PMID 29746493, 2018). "Moreover, promoter DNA methylation status of the CDO1 gene is well associated with CDO1 protein expression in EHCC tumor tissues." (PMID 30325974, 2018). "In this study, we investigated promoter DNA methylation status of the CDO1 gene in 172 primary BC tumor tissues, and strong association of CDO1 gene promoter DNA methylation with poor prognosis was shown in primary BC patients, especially for triple negative BC (TNBC)." (PMID 26785325, 2016). "This molecular mechanism may be associated with tumor suppressive function of CDO1 gene." (PMID 30934021, 2019). "In cell culture, Cdo1-overexpressing cells divide much slower and form many fewer tribes than other tumor cells." (PMID 38672271, 2024). "Although the tumor-suppressing effect of Cdo1 is mild, it plays important roles in assisting anticancer agents in overcoming drug resistance." (PMID 38672271, 2024). "In conclusion, Cdo1 conducts its tumor-suppressing role by reducing the antioxidants protecting cells from ferroptosis." (PMID 38672271, 2024). "High expression of Cdo1 leads to significant ferroptosis, reducing the number of tumor cells in many cases, and plays a role in suppressing cancer rather than targeting healthy cancer cells." (PMID 38672271, 2024).
tumor (continued). "Conversely, when DNMT3L expression is abnormal, DNMT3A can facilitate the methylation of CDO1 promoter, thus downregulating CDO1 expression and promoting tumor growth and metastasis." (PMID 38308276, 2024). "Here, developing drugs targeting Cdo1 is considered meaningful in neoadjuvant therapies, for example, helping against the development of anti-cancer drug resistance in tumor cells." (PMID 38672271, 2024). "Since the expression of Cdo1 is inhibited by methylation, its tumor-suppressing effects, including the promotion of apoptosis and ferroptosis, are limited." (PMID 38672271, 2024). "CDO1 is a tumor suppressor whose activity is silenced in diverse cancers via promoter methylation, a potential biomarker of tumor grade and progression." (PMID 38349720, 2024). "The methylation of the Cdo1 promoter is induced by Chd4/NuRD chromatin remodeling factors in tumor cells." (PMID 38672271, 2024). "These experimental findings provide additional evidence for the potential of CDO1 as an inhibitory factor for tumor growth and metastasis in HCC." (PMID 38308276, 2024). "The average tumour volume of xenografts tumours in CDO1‐overexpressing group and vector control group was 685.4 ± 123.3 and 1394.0 ± 128.8 mm3, respectively (p < .0001)." (PMID 37740473, 2023). "The degree of methylation of the CDO1 promoter is closely related to tumor progression and malignancy, and overexpression of CDO1 promotes ferroptosis in cancer cells." (PMID 38107069, 2023). "Overall, the tumour suppressor role of CDO1 in BC is complex due to the high heterogeneity of the disease, and further research is needed to investigate its mechanism in different pathological types of BC cell lines." (PMID 37740473, 2023). "As expected, both the CDO1 overexpression group and the CDO1 promoter‐targeted demethylation group exhibited significant growth retardation of tumours compared to the control mice." (PMID 37740473, 2023). "The performance of the CDO1 methylation biomarker in differentiating the BC cases from controls was better than that of traditional tumour antigen markers." (PMID 37740473, 2023). "The average tumour volume of xenografts tumours in CDO1 promoter‐targeted demethylation group and control group was 947.1 ± 118.8 and 1371.0 ± 134.2 mm3, respectively (p < .001)." (PMID 37740473, 2023). "To explore the role of CDO1 in GC, we firstly examined CDO1 expression in human GC and tumor-adjacent normal tissues." (PMID 36526626, 2022). "Collectively, these findings demonstrate that CDO1 impaired the proliferation of GC cells in vitro and tumor growth in vivo." (PMID 36526626, 2022). "Although numerous studies indicate that CDO1 has tumor-suppressive properties, divergent evidence in glioblastoma 55 highlights the necessity for additional research to determine the true impact of Cys-derived compounds on cancer metabolic reconstruction." (PMID 35280684, 2022). "Several types of cancer have their carcinogenesis associated with the silencing of physiologically beneficial genes, such as tumour suppressor genes, through DNA methylation in the article for CDO1." (PMID 33223534, 2021). "By analyzing differential RNA expression profiles with or without treatment with 5‐aza‐2′‐deoxycytidine, the frequency of CDO1 promoter methylation was observed with a statistically significant difference between normal and tumor tissues." (PMID 34056873, 2021). "The predominant notion, supported by a number of reports in different cancer types (detailed below), is that CDO1 is a tumour suppressor gene simply by virtue of its silencing in cancer; however, it is ought to be confirmed." (PMID 33223534, 2021).
tumor (continued). "For example, the methylation modification of CDO1 was common in multiple human cancer and the methylation silencing of CDO1 increased tumor cells growth." (PMID 33552157, 2021). "Recently, it was observed that cysteine dioxygenase type 1 (Cdo1) accumulation in LUAD generated in Keap1R554Q/R554Q mutant mice correlated with reduced tumor formation." (PMID 34440648, 2021). "As the quantity of circulating tumor DNA for detection is related to stage and tumor volume, we explored the diagnostic accuracy of the combination of best three genes (CDO1, SOX17, and HOXA7) according to tumor size." (PMID 32138766, 2020). "The methylation level of CDO1 was significantly different in the stratified comparison of gender, lymph node metastasis and tumor-node-metastasis (TNM) stage (P < 0.05)." (PMID 32317090, 2020). "The overall accuracy of the diagnosis was significantly higher than that of the clinical tumor markers, and the sensitivity of CDO1 to stage I and II patients was the highest (40.8%, 47.1%)." (PMID 32317090, 2020). "Age, procedures of gastrectomy, lymph node dissection, radical resection, tumor location, morphological type, pStage, and CDO1 TaqMeth V were significant (p < 0.05) prognostic factors in a univariate analysis." (PMID 30934021, 2019). "Among the various clinicopathological factors, positive correlation of CDO1 methylation with tumor diameter was observed (R = 0.31, p = 0.03), and the CDO1 methylation level was a possible prognostic factor for relapse-free survival (p = 0.09)." (PMID 30677088, 2019). "For demonstrating the tumor suppressive activity of CDO1 gene, only Kato III cells were considered to be appropriate." (PMID 30934021, 2019). "In this study, we can provide clinical evidence to support the possibility that methylation of CDO1 is involved in tumor cell proliferation." (PMID 30677088, 2019). "CDO1 TaqMeth V showed a significant difference according to age (p = 0.006; R2 = 0.070), histological type (p = 0.03), tumor diameter (p = 0.04; R2 = 0.038), and liver metastasis (p = 0.02)." (PMID 29746493, 2018). "CDO1 methylation was also significantly related to histological type, tumor diameter, liver metastasis, pT, Dukes classification, and v." (PMID 29746493, 2018). "In this study, we elucidated that CDO1 promoter DNA methylation accumulates along with tumor progression, and the highest level of CDO1 promoter DNA methylation was observed in CRC with liver metastasis." (PMID 29746493, 2018). "CDO1 DNA methylation was assessed by quantitative methylation-specific PCR in 108 BTC tumor tissues and 101 corresponding normal tissues." (PMID 30325974, 2018). "In this study, we didn’t evaluate any other tumor suppressor genes, however we believe that CDO1 gene would be one of the most excellent cancer-specific biomarkers for diagnostic exploration of BTC at present." (PMID 30325974, 2018). "The CDO1 methylation value in the tumor tissues was significantly higher than that in the corresponding normal tissues (p<0.0001)." (PMID 30325974, 2018). "Using this technique, we have identified novel tumor suppressor gene candidates including the cysteine dioxygenase type 1 (CDO1) gene in human cancers." (PMID 29161283, 2017). "There were significant correlations of CDO1 TaqMeth values with pStage (p = 0.027), primary tumor factor (pT) (p = 0.0060), macroscopic growth pattern (p = 0.044), and vascular permeation (p = 0.0082)." (PMID 29161283, 2017). "Jeschke also proved that promoter DNA methylation of CDO1 gene is significantly correlated with tumor progression and, intriguingly, prognostic relevance was found in primary BC patients who were treated by anthracycline." (PMID 26785325, 2016). "Using this technique, we have identified novel tumor suppressor gene candidates including cysteine dioxygenase type 1 (CDO1) gene in primary BC." (PMID 26785325, 2016).
tumor (continued). "U251 shCDO cells led to increased survival when compared with vector control (P = 0.01), with IHC performed on tumor sections confirming decreased CDO1 expression in these tumors." (PMID 24351290, 2014). "To examine the tumor suppressive role of CDO1 in an in vivo mouse model, we injected subcutaneously DLD-1-pCDO1-#2 and DLD-1-p3.1 clones into the right flanks of 6-week-old nude mice." (PMID 23028699, 2012). "We found a statistically significant difference in the frequency of CDO1 promoter methylation between primary normal and tumor tissues derived from colon, breast, esophagus, lung, bladder and stomach." (PMID 23028699, 2012). "A significant decrease of tumor volume was observed at the 4th week in mice injected with CDO1-expressing cells (989±408.1 mm3) compared to control mice (2,091±119.2 mm3) (P = 0.009)." (PMID 23028699, 2012). "Our data implicate CDO1 as a novel tumor suppressor gene and a potentially valuable molecular marker for human cancer." (PMID 23028699, 2012). "Tumor volume (mm3) was measured once a week for 4 weeks after injection, and tumor development of the control and CDO1 clones was first observed at day 8 and 11, respectively." (PMID 23028699, 2012). "All five tumor cases of colon tissue exhibited CDO1 down-regulation, and 3 of 5 cases of lung tissue displayed reduced levels of CDO1 in PT compared to PN." (PMID 23028699, 2012). "We also performed COBRA in parallel with the bisulfite-sequencing to corroborate CDO1 methylation in 10 pairs of randomly selected matched tumor (PT) and normal colon tissues (PN)." (PMID 23028699, 2012). "The CpG site cg12880658 affects the methylation of the CDO1 gene, and increased CDO1 expression can suppress cell proliferation, migration, and invasion in BC cells, exerting a tumor suppressor effect by inhibiting the cell cycle, promoting apoptosis, and ferroptosis." (PMID 40177272, 2025). "CDO1 alters cytosine metabolism, leading to the production of reactive oxygen species (ROS) and a reduction in cell viability and growth, and is considered to be a key tumor suppressor gene as well as a molecular marker of chemoresistance in cancer cells." (PMID 40221783, 2025). "Hence, it is possible that CDO1 has a significant impact on inhibiting tumor growth during tumorigenesis." (PMID 38681199, 2024). "Decreased CDO1 activity may support tumor cell growth by reducing reactive oxygen species and decreasing drug susceptibility." (PMID 38349720, 2024). "However, PDGDH and GLDC are overexpressed in many human cancer cells, whilst CDO1 is a known tumour suppressor gene in many human cancer cells." (PMID 39595653, 2024). "CDO1 hypermethylation detection can also be beneficial in intraoperative diagnosis during gastric cancer surgery and in evaluating routine biopsy samples for determining tumor eradication after neoadjuvant therapy for esophageal cancer." (PMID 38681199, 2024). "Cysteine dioxygenase type 1 (Cdo1) is a tumor suppressor gene." (PMID 38672271, 2024). "Cdo1 is considered a tumor suppressor as it enhances ferroptosis and apoptosis in cancer cells." (PMID 38672271, 2024). "CDO1 is hypermethylated and acts as a tumour suppressor gene in BC." (PMID 37740473, 2023). "Furthermore, we explored the potential mechanism of the CDO1 anti‐tumour effect and found that CDO1 overexpression arrested cell cycle progression and promoted cell apoptosis and ferroptosis in BC cells." (PMID 37740473, 2023). "Additionally, we found that CDO1 exerted a tumour suppressor effect by inhibiting the cell cycle, promoting cell apoptosis and ferroptosis." (PMID 37740473, 2023).